RORA (RAR related orphan receptor A)
Diseases named in the same sentence as RORA in open-access papers (continued):
Sharing a sentence is not in itself a finding about the gene and the disease.
allergic rhinitis (3 papers, 2022 to 2025). Inflammation of the nasal mucous membranes caused by an IgE-mediated response to external allergens. "The objective of this study was to explore the function and mechanism of RORα in allergic rhinitis (AR)." (PMID 37904695, 2023). "For example, overexpression of RORA reduced red blood cell infiltration and nasal mucosal injury in allergic rhinitis through blockade of Wnt/β-catenin signaling pathway." (PMID 35195816, 2022).
cardiomyopathy (3 papers, 2022 to 2023). A disease of the heart muscle or myocardium proper. "In the EWAS, we identified cg15939386 in the RORA gene to be significantly associated with anthracycline-induced cardiomyopathy." (PMID 37542143, 2023). "Mice with a loss-of-function mutation in RORα (Rorasg/sg) have impairments in the circadian oscillator and develop severe cardiomyopathies." (PMID 35743288, 2022).
Crohn disease (3 papers, 2015 to 2023). A gastrointestinal disorder characterized by chronic inflammation involving all layers of the intestinal wall, noncaseating granulomas affecting the intestinal wall and regional lymph nodes, and transmural fibrosis. "Moreover, in a Salmonella-driven model of Crohn’s disease-like fibrosis, we showed that RORα-deficient mice were protected: RORα inactivation dampened Th17/ILC3-type cytokine production, including IL-17 and IL-22." (PMID 36052086, 2022).
cutaneous melanoma (3 papers, 2019 to 2023). A primary melanoma arising from atypical melanocytes in the skin. "Similarly, to cutaneous melanoma cells, RORα and RORγ were found to be expressed in both the nuclei (RORαn, RORγn), and the cytoplasm (RORαc, RORγc) of uveal melanoma and normal tissue." (PMID 31235702, 2019). "Also in skin melanoma, a significantly decrease in the expression of VDR, CYB27B1, CYP24A1, RORα and RORγ was observed in comparison to normal melanocytes or perilesional keratinocytes." (PMID 31235702, 2019).
emphysema (3 papers, 2021 to 2023). "Further, RORα inhibitor, SR1001, presented a therapeutic effect in hypoxia-induced pulmonary hypertension, and the expression of RORα was upregulated after CS exposure as well as in patients with COPD/emphysema compared with healthy controls." (PMID 34014841, 2021). "Moreover, RORα levels are elevated in the lungs of COPD patients, but interestingly, RORα-deficient mice are protected against emphysema induced by elastase and CS exposure." (PMID 38067152, 2023). "The inhibition of RORα can protect against emphysema and regulates autophagy flux." (PMID 35509068, 2022). "Thus, it has been suggested that RORα is important in promoting emphysema through epithelial cell apoptosis." (PMID 35509068, 2022).
endotoxemia (3 papers, 2021 to 2023). "Treatment of mice with a RORα selective synthetic inhibitor also reduced the severity of LPS-induced endotoxemia." (PMID 33767712, 2021). "Treatment with selective RORα inhibitor also reduced the severity of LPS‐induced endotoxemia." (PMID 37051760, 2023).
experimental autoimmune encephalomyelitis (3 papers, 2019 to 2022). An autoimmune demyelinating disease of the central nervous system that is produced experimentally in animals by the injection of homogenized brain or spinal cord in Freund's adjuvant. "Although it is established that RORγt is required for Th17 cell differentiation, it has been reported that RORα can partially compensate for RORγt deficiency to promote Th17-dependent experimental autoimmune encephalomyelitis (EAE)." (PMID 36243007, 2022).
Granuloma (3 papers, 2022 to 2024). A compact, organized collection of mature mononuclear phagocytes, which may be but is not necessarily accompanied by accessory features such as necrosis. "Further supporting a hybrid cell state, we independently confirmed the presence of a subset of granuloma T cells expressing both T-bet and RORα by flow cytometry." (PMID 35483355, 2022).
Intellectual disability (3 papers, 2022 to 2025). "For example, mutations in the RORα gene (RORA) link to intellectual disability including autistic symptoms." (PMID 41408339, 2025).
leukemia (3 papers, 2021 to 2025). A malignant (clonal) hematologic disorder, involving hematopoietic stem cells and characterized by the presence of primitive or atypical myeloid or lymphoid cells in the bone marrow and the blood. "Expression of RORα has been observed in multiple cancers, including gastric, cervical, pancreatic cancers, leukemia, lymphoma, myeloma, and bladder cancer." (PMID 41425709, 2025). "Confirmation of this analysis was conducted by qPCR (for RORA mRNA) in freshly isolated Ph+ B-ALL patient leukemia cells (B220+) and healthy donor B cells (B220+)." (PMID 35414788, 2022). "The qPCR results were consistent with the dataset analysis, which revealed that RORA expression was significantly decreased in leukemia cells when compared to healthy B cells." (PMID 35414788, 2022). "RORA is the key regulator of embryonic development and cellular differentiation, whose upregulation may promote the proliferation of the leukemia cells." (PMID 33408321, 2021). "Compared to healthy BMMCs, we observed the TF networks of ZNF266, RORA, GTF3C2, ZNF76, ZNF383, IRF5 and NFE2L2 being top upregulated in all leukemia patients." (PMID 33408321, 2021).
liver cancer (3 papers, 2021 to 2025). An epithelial or non-epithelial malignant neoplasm that arises from the liver. "RORα mediates the glucose metabolism-reprogramming response to glutamine deprivation and contributes to altered glucose utilization and liver cancer growth." (PMID 38725854, 2024). "Studies have confirmed that downregulation of RORα is a clinical feature of liver cancer." (PMID 41425709, 2025). "RORα knockdown facilitates EMT via the Wnt/β-catenin pathway and enhances the proliferation, invasion, and metastasis of liver cancer." (PMID 41425709, 2025). "Conversely, the expression levels of ARNTL, NR1D1, PER1, PER2, PER3, PRKAG2, and RORA were not significantly related to the OS of liver cancer patients." (PMID 34149816, 2021).
lung adenocarcinoma (3 papers, 2021 to 2025). A carcinoma that arises from the lung and is characterized by the presence of malignant glandular epithelial cells. "Similarly, by multi-omics computation techniques, several core circadian clock genes are found changed epigenetically in lung adenocarcinomas and lung squamous cell carcinomas, which are involved in cell cycle and apoptosis, such as PER2 and RORA." (PMID 33816508, 2021).
lung diseases (3 papers, 2022 to 2024). "A previous study also reported the role of RORα in DNA damage as it is related to smoking-related lung diseases." (PMID 35509068, 2022). "A link between RORα and autophagy has also been established in relation to human lung diseases." (PMID 39518891, 2024).
migraine (3 papers, 2020 to 2025). "In the present study, for the first time, we described that RORA rs4774388 is significantly related to the migraine susceptibility." (PMID 32892507, 2020). "Therefore, in this study, for the first time, we aimed to investigate the association of RORA rs11639084 and rs4774388 variants with migraine susceptibility in Iranian patients." (PMID 32892507, 2020). "RORA may contribute to migraine susceptibility and some symptoms through the regulation of Th17‐cell differentiation of and the circadian rhythm." (PMID 32892507, 2020). "Further research considering the role of RORA in migraine may enhance our understanding of the mechanisms underlying this gene." (PMID 32892507, 2020). "Therefore, we recommend RORA as a new susceptible locus in migraine, which may offer new therapeutic intervention." (PMID 32892507, 2020). "These were likely attributable to the pleiotropic effects of RORα agonism on circadian rhythm (a known factor in migraine) and neutrophil migration, respectively." (PMID 41010352, 2025). "Further studies in different ethnicities are required to confirm the function of RORA in migraine development." (PMID 32892507, 2020). "Considering the crucial role of RORA in the regulation of inflammation and circadian rhythm, it would be a good therapeutic target in migraine treatment." (PMID 32892507, 2020). "RAR‐related orphan receptor (RORA) involves in regulation of several biological processes including inflammation and circadian rhythm that probably are involved in migraine pathophysiology." (PMID 32892507, 2020). "Current results suggest RORA, as a molecular link, may explain inflammation and circadian rhythm dysfunction in migraine." (PMID 32892507, 2020). "Current results suggest RORA may serve as a molecular link between inflammation and circadian rhythm dysfunction in migraine." (PMID 32892507, 2020). "Besides the regulation of cytokine‐mediated signaling pathway and inflammatory response, RORA seems to regulate several migraine‐related pathways, including circadian rhythm, cellular response to hypoxia, nitric oxide biosynthesis, and VEGF production." (PMID 32892507, 2020).
osteosarcoma (3 papers, 2016 to 2023). A usually aggressive malignant bone-forming mesenchymal neoplasm, predominantly affecting adolescents and young adults. "Downregulation of RORα or Bmal1 in U2OS osteosarcoma cells attenuates the MLN4924-induced cell growth suppression as well as G2/M cell cycle arrest." (PMID 27602774, 2016). "RORα was significantly up-regulated in osteosarcoma MG63, Saos-2, and U2OS cells after MLN4924 (1 μM) treatment." (PMID 27602774, 2016). "RNA interference of RORα attenuates the anti-proliferative effect of MLN4924 in U2OS osteosarcoma cells." (PMID 27602774, 2016). "In this study, we have demonstrated that MLN4924 decreases the ubiquitination of RORα and subsequently its degradation in osteosarcoma cells." (PMID 27602774, 2016). "To investigate whether MLN4924 affects the degradation of RORα, we first examined the endogenous RORα protein levels in osteosarcoma cells treated 24 h with MLN4924." (PMID 27602774, 2016). "In this study, we show that MLN4924 suppresses the proliferation of osteosarcoma cells, which may be mediated, at least partly, through the retinoid orphan nuclear receptor alpha (RORα)." (PMID 27602774, 2016). "In addition, we have demonstrated that the circadian clock components RORα and Bmal1 play important roles in the MLN4924 effect in osteosarcoma cells." (PMID 27602774, 2016). "Although p21 is transcriptionally regulated by RORα, and p21 was indeed upregulated after MLN4924 treatment in U2OS osteosarcoma cells, p21 does not seem to play a significant role in the effect of MLN4924 in U2OS cells." (PMID 27602774, 2016).
pancreatic cancers (3 papers, 2015 to 2025). "Interestingly, RORA is part of the core circardian genes and variants in these gene were previously reported to be associated to several cancers, including breast, prostate and pancreatic cancers." (PMID 34996381, 2022).
post-traumatic stress disorder (3 papers, 2015 to 2019). An anxiety disorder precipitated by an experience of intense fear or horror while exposed to a traumatic (especially life-threatening) event. "The RORA gene was selected based on its association with posttraumatic stress disorder (PTSD) in the first PTSD genome wide association study." (PMID 25798337, 2015).
spinocerebellar ataxia type 1 (3 papers, 2017 to 2024). Spinocerebellar ataxia type 1 (SCA1) is a subtype of type I autosomal dominant cerebellar ataxia (ADCA type I) characterized by dysarthria, writing difficulties, limb ataxia, and commonly nystagmus and saccadic abnormalities. "Ataxin-1, linked to spinocerebellar ataxia type 1, is known to interact with the orphan nuclear receptor RORα." (PMID 29192206, 2017). "It seems a possible link between RORα and pathogenesis of Spinocerebellar ataxia type 1 (SCA1) is via decreasing the number of cerebellar Purkinje cells." (PMID 28042538, 2017).
age-related macular degeneration (2 papers, 2011 to 2017). Age-related loss of vision in the central portion of the retina (macula), secondary to retinal degeneration. "ROBO1 is a strong candidate gene for age-related macular degeneration (AMD) based upon its location under a linkage peak on chromosome 3p12, its expression pattern, and its purported function in a pathway that includes RORA, a gene previously associated with risk for neovascular AMD." (PMID 21998696, 2011).
cerebellar degeneration (2 papers, 2017 to 2020). Degeneration of the cerebellum. "Partial loss of TIP60 delays cerebellar degeneration in SCA1[82Q] transgenic mice and correlates with an increased level of RORa and RORa-dependent gene expression." (PMID 32581696, 2020). "It is possible that YAP/YAPdeltaC influence apoptosis and increase resistance against SCA1-associated cerebellar degeneration, including the reduction in Purkinje cell numbers, independently of the hypothesized effect of YAP/YAPdeltaC on RORα-mediated transcription." (PMID 29192206, 2017).
cholangiocarcinoma (2 papers, 2025). A carcinoma that arises from the intrahepatic biliary tree (intrahepatic cholangiocarcinoma) or from the junction, or adjacent to the junction, of the right and left hepatic ducts (hilar cholangiocarcinoma). "Our analysis revealed that RORC amplification and elevated mRNA levels were detected in 20% of cholangiocarcinoma cases, compared to other members of the ROR family, including RORA and RORB." (PMID 41430037, 2025).
chronic obstructive pulmonary disease (2 papers, 2022). A chronic and progressive lung disorder characterized by the loss of elasticity of the bronchial tree and the air sacs, destruction of the air sacs wall, thickening of the bronchial wall, and mucous accumulation in the bronchial tree. "Retinoid-related orphan receptor-α (RORα) and autophagy dysregulation are involved in the pathophysiology of chronic obstructive pulmonary disease (COPD), but little is known regarding their association." (PMID 35509068, 2022).
cognitive deficits (2 papers, 2017 to 2025). "Two heterozygous pathogenic variants in SQSTM1 and RORA was detected in patient HA72, a 61 year-old female diagnosed with upper limb spasticity, ataxic gait and mild cognitive impairment." (PMID 40208338, 2025). "As a result, four SNPs, including the RORA-rs13329238, NPAS2-rs17655330, CLOCK-rs3749473, and RORB-rs10781247 SNPs individually and interactively alters the hazard of cognitive deficits in terms of MMSE scores for normal aging." (PMID 29209239, 2017).
Glucose intolerance (2 papers, 2013 to 2020). Glucose intolerance (GI) can be defined as dysglycemia that comprises both prediabetes and diabetes. "RORα has a known role in the progression of metabolic disease, with Rorasg/sg mice refractory to weight gain and glucose intolerance associated with feeding a high-fat diet." (PMID 32973801, 2020).
helminth infection (2 papers, 2018 to 2023). "To further explore the roles for RORα in immune cells during helminth infection, we used Rorasg/sg mutant mice, which produce a ubiquitously expressed, truncated form of the RORα protein to generate Rorasg/sg BMC mice." (PMID 37387671, 2023). "Indeed, we demonstrated that mice whose T cells lack RORα mounted equivalent type 2 adaptive immune responses to parasitic worm infection, papain allergen, and IL-33 as RORα-sufficient T cell controls." (PMID 29907525, 2018).
inflammatory skin disease (2 papers, 2023 to 2024). Inflammatory skin disorders covers a broad category that includes many conditions ranging in severity, from mild itching to grave medical health complications These disorders are common in people of all ages and races. "Accordingly, we expect that the major epidermal RORα reduction in skin lesions of diverse inflammatory skin diseases can amplify contact allergy and accelerate disease progression." (PMID 39409027, 2024). "Recent reports revealed that the epidermal RORα levels are significantly downregulated in clinical samples of several inflammatory skin diseases, including allergic contact dermatitis, lichen simplex chronicus, and sarcoidosis." (PMID 39409027, 2024). "Clinical studies showed that the epidermal RORα expression is significantly reduced in the lesions of multiple inflammatory skin diseases." (PMID 39409027, 2024). "A recent study demonstrated that epidermal RORα protein expression is significantly lower in human skin lesions of several inflammatory skin diseases than in normal skin." (PMID 37373387, 2023). "In contrast, epidermal RORα expression was downregulated in the skin lesions of several inflammatory skin diseases, including AD." (PMID 37373387, 2023). "Our findings also revealed the beneficial potentials of RORα agonists to restore barrier functions and alleviate inflammation in treating AD and other inflammatory skin diseases." (PMID 37373387, 2023). "Recent reports have shown that epidermal RORα levels are significantly down-regulated in clinical samples of several inflammatory skin diseases, including allergic contact dermatitis, lichen simplex chronicus, sarcoidosis, and AD." (PMID 37373387, 2023). "Importantly, these findings ascertain the beneficial potentials of RORα-selective agonists in restoring epidermal structural components and barrier functions for treating AD and other inflammatory skin diseases." (PMID 39409027, 2024). "Furthermore, while epidermal RORα expression is downregulated in skin lesions of multiple inflammatory skin disorders, including AD, its expression is unaltered in psoriatic skin lesions." (PMID 37373387, 2023).
injury (2 papers, 2018 to 2019). Damage inflicted on the body as the direct or indirect result of an external force, with or without disruption of structural continuity. "Finally, the genetic variant in RORA, rs8042149, which was identified in the first GWAS for PTSD was unfortunately not included on our genotyping array, thus we were not able to assess whether this particular allele predicted PTSS in our trauma cohorts." (PMID 30498461, 2018).
ischemia (2 papers, 2014 to 2023). A hypoperfusion of the BLOOD through an organ or tissue caused by a PATHOLOGIC CONSTRICTION or obstruction of its BLOOD VESSELS, or an absence of BLOOD CIRCULATION. "Both genetic deficiency and pharmacological inhibition of RORα worsened laser-induced CNV, suggesting an anti-angiogenic role of RORα in CNV, in line with a previous study in a hind limb ischemia model that reported increased ischemia-induced angiogenesis in Rorasg/sg mice." (PMID 36626253, 2023).
leiomyosarcoma (2 papers, 2018 to 2022). An uncommon, aggressive malignant smooth muscle neoplasm, usually occurring in post-menopausal women. "Employing an additive model of inheritance CLOCK rs1801260 and PER2 rs934945 were statistically significantly associated with liposarcoma, while NPAS2 rs895520 and RORA rs339972 were statistically significantly associated with leiomyosarcoma." (PMID 30518396, 2018).
lymphoma (2 papers, 2021 to 2025). A malignant (clonal) proliferation of B- lymphocytes or T- lymphocytes which involves the lymph nodes, bone marrow and/or extranodal sites. "In our results, some of the differentially methylated genes in EHMT2 + MCL cases have also been reported with recurrent genetic alterations in lymphoma, such as ALK, DUSP22, NCOR2, RORA, DLC1, JAG1/2, JAK1, NOTCH4, and CD1938–45." (PMID 34633777, 2021).
neuropathy (2 papers, 2018 to 2023). A disorder affecting the nervous system that manifests with pain, tingling, numbness, and/or muscle weakness. "Using GWA study, we found four SNPs in four genes (SNX8; PCP2; KNG1; and RORA) to be statistically significantly associated with neuropathy." (PMID 29884837, 2018).